AFP (alpha fetoprotein)
Diseases named in the same sentence as AFP in open-access papers (continued):
Sharing a sentence is not in itself a finding about the gene and the disease.
tumor (continued). "Combination of simultaneous elevation of tumor makers (AFP and CA19-9) and tumor mark elevation in discordance with presumptive imaging findings on CEUS or CT may lead significantly more patients to be suspicious of the diagnosis of cHCC-CC." (PMID 26917546, 2016). "Univariate analysis revealed that ZC3H15, serum AFP, HBV, tumor size, venous invasion, and UICC stages could serve as predictors for OS or/and DFS." (PMID 27191988, 2016). "AFP and ALT are also very widely used tumor markers in HCC diagnosis and management." (PMID 27329727, 2016). "Furthermore, tumor site (HR: 2.242; 95% CI: 1.052-4.1774; p=0.036), higher TNM stage (HR: 2.441; 95% CI: 1.616-3.688; p=0.000), and AFP positivity (HR: 2.9441; 95% CI: 1.573-5.509; p= 0.001) were associated with unfavorable OS." (PMID 27057629, 2016). "The tumor marker of all cases, including CA-125, CA-19-9, CEA, AFP, were normal." (PMID 26739518, 2016). "This study will allow us to evaluate the individual effect of decreasing AFP without considering the tumor volume." (PMID 25822740, 2015). "The expression level of TRIM35 was negatively correlated with the tumor size, histological grade, and AFP concentration (data not shown)." (PMID 25576919, 2015). "With the application of PDMS microfluidic channels, we utilized a dual-channel setup to functionalize the surface of the biosensor with both AFP and CEA antibodies on different SiNWs, making it clinically reliable to detect the concentrations of the two tumor makers, AFP and CEA, simultaneously." (PMID 26251912, 2015). "This may be due to the fact that plasma tumour marker levels (HCG, AFP and LDH) are categorical in the IGCCC, and used as continuous variables in our analysis." (PMID 25811459, 2015). "Patients with negative AFP have a low occurrence of tumor vascular invasion and tend to exhibit healthier hepatic function." (PMID 25633810, 2015). "To confirm whether miR-1236 contributes to high AFP levels in HCC patients, we first examined the expression of miR-1236 and AFP in 20 pairs of HCC tissues and adjacent non-tumor tissues using qRT-PCR." (PMID 25714026, 2015). "After 2 weeks of sorafenib therapy, there were 26 patients (45.6%) without disappearance of arterial tumor enhancement on CE-CT, 15 patients (26.3%) with an AFP ratio of >1.2, and seven patients (12.3%) with two or more increments in the CP score." (PMID 26421430, 2015). "Functions of AFP includes, its use as growth and differentiation factors for embryonic stem cells and tissues, operates as a suppressive factor for tumours or activated immune cells, and does not affect the proliferation of normal untransformed cells." (PMID 26158863, 2015). "The tumor cells were positive for chromogranin A, synaptophysin, CD99, cytokeratin 19, pan-cytokeratin and β-catenin, and also showed diffuse immunoreactivity for AFP and human chorionic gonadotrophin." (PMID 25886790, 2015). "In addition, age, tumor size, venous invasion, Child-Pugh status, TNM stage, AFP, GGT, ALB, and ALT remained significant recurrence predictors." (PMID 26656354, 2015). "Curcumin alone did not have any significant influence on AFP concentrations or tumor volume in vivo." (PMID 26515460, 2015). "A nomogram predicting FFR was developed, incorporating non-neoplastic liver cirrhosis, multifocality, preoperative alpha-fetoprotein level, Child-Pugh score, vascular invasion, tumor size, surgical margin and symptoms at presentation." (PMID 25830231, 2015). "Multivariate analysis by cox-regression revealed that AFP (P = 0.004), CHILD PUGH grade (P = 0.018), BCLC stage(P = 0.002), Platelet count (PLT)(P = 0.011), the number of tumors (P = 0.018), tumor size(P = 0.010)and H101 (P = 0.048) were independent prognostic factors of OS." (PMID 26470869, 2015). "AFP value more than 100 thereby conferring an increased anti-tumor suppressive response as compared to non-HBV-HCC patients." (PMID 25767469, 2015).
tumor (continued). "In week 15, MRI scans showed that the size of tumor lesion declined by more than 96.9% to 2.8 cm × 1.7 cm × 2 cm; there was no tumor activity in the artery phase; and the AFP level was close to the normal range, 54.33 ng/ml." (PMID 25649133, 2015). "Hepatic lesion, ovarian tumor or possible AFP producing tumor of the other site was not evident by ultrasound scan and MRI." (PMID 26337640, 2015). "We then attempt to further investigate the prognostic value of peritumoral Cbl in HCC subgroups with small tumor (maximum diameter ≤ 5 cm, n = 134), low AFP level (≤ 400 ng/ml, n = 135), no microvascular invasion (n = 132) and negative HBeAg (n = 144)." (PMID 26474280, 2015). "HCC tumor specimens (n=47) were separated into AFP mRNA positive (n=25) and negative groups (n=22); miR-93 expression was significantly higher in the AFP positive group compared to the negative group (p=0.048, student t-test)." (PMID 25633810, 2015). "AFP may be involved in the PI3K/Akt signaling pathway, and PTEN, a tumor suppressor, is a negative regulator in this pathway." (PMID 25714026, 2015). "Post treatment surveillance comprises of history, examination, measurement of the tumour markers beta human chorionic gonadotrophin (beta HCG) and alpha feto-protein (AFP), and radiological surveillance with chest radiographs and computed tomography (CT) at regular intervals." (PMID 26428307, 2015). "In addition, tumor size, TNM stage, Child-Pugh class and laboratory findings, such as AFP and Hs-CRP remained significant recurrence predictors." (PMID 25970775, 2015). "However, when tumor markers were categorized using the cut-points in the IGCCC, only AFP level remained as a significant prognostic marker." (PMID 25811459, 2015). "Tumor markers (LDH, HCG, and AFP) should be collected postorchiectomy for cancer staging." (PMID 25705542, 2015). "Furthermore, we confirmed the regulatory effect of miR-212 on FOXA1, AFP and YAP in xenograft tumor tissue." (PMID 25965836, 2015). "Tumor markers (hCG, AFP, and LHD) are typically negative, but endocrine anomalies such as elevated testosterone or estrogen are sometimes observed." (PMID 26525589, 2015). "In addition, age, tumor size, venous invasion, Child-Pugh status, TNM stage, AFP, GGT, ALB, and ALT remained significant death predictors." (PMID 26656354, 2015). "Liver function was significantly better (Child-Pugh A 64.6% vs. 43.6%, p = 0.012) and tumor size was smaller (median 10.3 cm vs. 12.0 cm, p = 0.027) in AFP responders than in AFP non-responders." (PMID 26252472, 2015). "Unfortunately, AFP serum concentrations do not correlate well with the prognostic values of HCC such as tumor size, stage, or disease progression." (PMID 26097877, 2015). "Our results showed that age (RR, 1.60; RR, 0.40-2.65), gender (RR, 1.53; 95% CI, 0.50-2.95), tumor size (RR, 2.25; 95% CI, 0.95-4.34), and AFP (RR, 1.38; 95% CI, 0.58-2.64) were not independent predictor of the survival of patients with HCC." (PMID 25552204, 2014). "In patients with LCTs the blood tests for tumor markers (AFP, β- hCG, and lactate dehydrogenase) are negative." (PMID 25230718, 2014). "Patient 8 expanded AFP-specific T cells and anti-AdV antibodies, but had minimal AdV-specific T cells and recurred at a later time, with an AFP-negative tumor." (PMID 24708667, 2014). "Besides high KIF18A expression, size of tumor ≥5cm, multiple tumor number, III-IV of TNM stage, the AFP value (≥200 ng/ml), recurrence together with PVTT and distant metastasis were associated with a shorter DFS and OS." (PMID 25431949, 2014). "At immunohistochemical examination tumor cells stained positive with chromogranin A and synaptophysin antibodies and were negative for hepatocyte, AFP, and CD56 antibodies." (PMID 24653852, 2014).
tumor (continued). "The four most upregulated genes were pepsinogen C (PGC), alpha fetoprotein (AFP), aldoketo reductase family 1 member B10 (AKR1B10) and glypican 3 (GPC3), which showed greater than 30-fold higher expression in HCC tumors than adjacent non-tumor tissues." (PMID 25217841, 2014). "Exploiting such virosomal delivery, the alpha-fetoprotein (AFP) promoter, in combination with various tumour specific enhancers, was used to drive the expression of shRNA directed against ME1a1 binding site of the proto-oncogene c-Myc P2 promoter, in order to induce TGS in neoplastic liver cells." (PMID 25108398, 2014). "In our studies, GPC3 immunoreactivity was detected in 103 of 136 HCC cases (75.7%), and GPC3 expression was closely related with HBsAg positivity, but not with sex, HCC differentiation, age, serum AFP level, tumor size, and extrahepatic metastasis." (PMID 24498024, 2014). "When outcomes were analyzed within treatment groups, patients with low pre- and post-treatment serum AFP levels and small tumor size tended to survive longer, but not significantly so." (PMID 24993566, 2014). "Nodal protein was expressed in 70 of the 96 (72.9%) HCC tumors, and was associated with vascular invasion (P = 0.000), status of metastasis (P = 0.004), AFP (P = 0.049), ICGR15 (indocyanine green retention rate at 15 min) (P = 0.010) and tumor size (P = 0.000)." (PMID 24465741, 2014). "Hormonal investigations made after surgery showed still the persistence of a moderate increase of serum level of E2, while tumor markers AFP and β-hCG were still negative." (PMID 25230718, 2014). "Other reports found that in hepatic tumour patient with paraneoplastic syndromes, both the AFP and tumour size are higher than those without paraneoplastic syndromes." (PMID 25525545, 2014). "Neither AFP reduction nor decrease of tumour mass were observed, but treatment improved both median survival time and QoL." (PMID 25225571, 2014). "Traditional clinicopathological parameters such as tumor morphology, histopathological features, concentration of serum alpha fetoprotein (AFP) and tumor stage offer limited information for prognosis prediction and fail to guide the therapeutic schedule for individual patient." (PMID 24718422, 2014). "Serum tumor markers revealed a beta-human chorionic gonadotropin (hCG) of 3804mIU/mL (<5mIU/mL), lactose dehydrogenase (LDH) of 196U/L (100 to 190U/L) and an alpha-fetoprotein (AFP) of 47.7ng/mL (0.0 to 9.0ng/mL)." (PMID 24380446, 2014). "Serum tumor markers, including β-human chorionic gonadotropin and α-fetoprotein (AFP), were not measured, as a diagnosis of GCT was not suspected at this stage." (PMID 25202397, 2014). "By contrast, the tumor cells in the tumor described were negative for AFP, HepPar-1, K7, K19, CD34, CD56 and CD133, and positive for C-KIT and EpCAM." (PMID 25202388, 2014). "The tumor markers (AFP and β-hCG) were also negative and hormonal investigations were normal, except moderately elevated estradiol level (E2) and low normal level of testosterone (T)." (PMID 25230718, 2014). "Factors associated with shorter survival at multivariate analysis were tumor >5 cm, absence of CR, ascites, alpha-fetoprotein (AFP) ≥14.5 ng/mL and a MELD increase ≥1." (PMID 25139639, 2014). "However, MMP2 mRNA and protein levels were positively correlated with AFP levels, clinical TNM stage, tumor size and metastasis." (PMID 25013467, 2014). "Furthermore, serum AFP, TNM stage, tumor differentiation, and vascular invasion were also significantly associated with OS, and serum AFP, TNM stage, vascular invasion were significantly associated with TTR." (PMID 23537217, 2013). "Overall, it appears that both the tumor burden (assessed as the total tumor volume [TTV] or the maximum tumor size) and biological factors, such as alpha fetoprotein (AFP), best predict outcome, and these factors can help maintain low rates of post-transplant recurrence." (PMID 22710887, 2013).
tumor (continued). "However, after multivariate survival analysis only the lesion diameter, Child-Pugh classification, alcohol-related cirrhosis, tumor response according to EASL criteria and AFP prior the session were independent prognostic factors of survival." (PMID 24198841, 2013). "Association of clinicopathologic features with signal transducer and activator of transcription 3 (STAT3) expression in the primary tumor of alpha-fetoprotein (AFP)-positive and -negative gastric cancers." (PMID 23382965, 2013). "The case in this study displayed normal serum AFP level and no background chronic liver disease, with significant tumor thrombus." (PMID 23599762, 2013). "The tumour markers alpha-fetoprotein (AFP) and human chorionic gonadotropin (ß-HCG) were not increased." (PMID 23406299, 2013). "Alpha-fetoprotein (AFP) and glypican-3 are current tumor markers for HCC." (PMID 24244607, 2013). "Tumor markers carcinoembryonic antigen, alpha-fetoprotein, and CA19-9 levels in the peripheral blood were not elevated at any time." (PMID 23714181, 2013). "Studies have demonstrated that the α-fetoprotein (AFP), carcinoembryonic antigen (CEA), ubiquitin C (UbC), murine albumin (mAlb), prostate-specific antigen (PSA) and the glucose transporter gene 1 (GTI-1.3) promoters all lead to tumor-specific hNIS expression." (PMID 23420532, 2013). "High levels of IL-6 and IL-10 are observed in HCC patients, correlate with tumor size, and may be helpful to identify a subset of HCC patients with low AFP level." (PMID 27335826, 2013). "AFP and/or DCP responders were stratified into combined tumor marker responders (cTM responders, n = 99) whereas subjects without AFP and DCP responses were stratified into cTM non-responders (n =16)." (PMID 23282286, 2013). "The poor prognosis is observed at the condition of high AFP level because the tumor exhibits a tendency to metastasize to the liver, even if the tumor is no deeper than the submucosa." (PMID 24083471, 2013). "In addition, Child-Pugh class, tumor size, EHS and/or RNI, AFP level ≥400 ng/mL, PIVKA level ≥1,000 AU/L, and the cumulative dose of sorafenib (transformed by natural logarithm) significantly predicted PFS in univariate analysis (all P < 0.05)." (PMID 24155932, 2013). "In the current case report, the patient had no previous medical history and enhanced CT showed a neoplasm mimicking cancer with atypical symptoms and a negative AFP value, making the formation of a diagnosis difficult." (PMID 24137445, 2013). "The protein expression of PTP4A3/PRL-3 was significantly correlated with tumor differentiation (P < 0.0001), serum AFP (P = 0.0118), high serum PIVKA-II (P = 0.0214), hepatic vein invasion (P = 0.0374), tumor vascular invasion (P = 0.0198), and advanced cancer stages (P = 0.0047)." (PMID 23064776, 2013). "Upon multivariate analysis, the PIVKA-II and AFP responses were significant indicators of overall survival independent of host, tumor, and serological factors, when pretreatment values were compared with those 3 and 6 months after treatment." (PMID 24455683, 2013). "When we consider that only viable HCC can produce AFP and that the mRECIST criteria were developed to evaluate the amount of viable HCC, it is not surprising that AFP response showed a significant correlation to tumor response evaluated by mRECIST criteria." (PMID 23282286, 2013). "In addition, age, HBsAg, serum AFP, TNM, and tumor differentiation differed significantly between GPC3-low and GPC3-high patients, and these results were similar to those from previous reports." (PMID 23537217, 2013). "A higher expression of MACC1 mRNA was significantly associated with ages, tumor size, portal vein trunk invasion, multinodular and poorly tumor differentiation, but not with gender, lesion number, AFP level or Child-Pugh class." (PMID 23414367, 2013).
tumor (continued). "AFP level, number and total diameter of tumor nodules, Milan criteria, UCSF criteria, PET status, microvascular invasion, tumor differentiation, lymphatic and vascular invasion, and tumor response to IBT correlated significantly with outcome in the IBT subpopulation." (PMID 23349774, 2013). "Because of the relationship with tumor burden and outcomes, several centers are now using highly elevated levels of AFP to rule out patients for liver transplantation." (PMID 24455285, 2013). "In addition, Child-Pugh class, tumor size, EHS and/or RNI, AFP level ≥400 ng/mL, PIVKA level ≥1,000 AU/L, and the cumulative dose of sorafenib (transformed by natural logarithm) significantly predicted OS in univariate analysis (all P < 0.05)." (PMID 24155932, 2013). "Since PLK4 expression was significantly corrected to AFP, tumor size and clinical stage, we further determined the relationship between PLK4 expression and the survival of patients subclassified as ‘large tumor’, ‘AFP (≥20 ng/ml)’ and ‘Stage (III–VI)’." (PMID 22829937, 2012). "There were no facility for assay of tumour markers such as human chorionic gonadotropin (hCG), alpha fetoprotein (AFP), or carbohydrate antigen 125 (CA-125)." (PMID 22852103, 2012). "Furthermore, serum clusterin levels were above the cut-off value in 5 of 12 HCCs (41.7%) in whom both serum AFP and PIVKA-II were within their cut-off values, suggesting that clusterin is complementary to the conventional two representative HCC tumor markers." (PMID 22957256, 2012). "Historically, AFP has been mainly tested in the diagnostic mode rather than for HCC surveillance after any type of tumor treatment; consequently, AFP has been introduced as a variable in the flowcharts used for HCC diagnosis in both Europe and the USA." (PMID 22792474, 2012). "It seems that the anti-tumor immunity provoked by RT-DC is not PSA or AFP-specific, but CT-26 cell-specific." (PMID 23112956, 2012). "Ad-AFpg-DN-PP2Acα restrained the tumor growth of AFP-positive xenografts in vivo, but did not affect AFP-negative xenografts." (PMID 23173703, 2012). "Furthermore, some other tumor markers, such as GPC3, GGT II, AFU, have been shown to be supplementary to AFP and DCP in the detection of HCC." (PMID 22655201, 2012). "Treatment options for HCC (resection), level of GGT (≤ 50 U/L) and AFP (≤ 25 ug/L), tumor number (solitary), vascular invasion (absent), and TNM stage (TNM stage I) were significant factors associated with favorable HCC-specific OS in univariate analysis." (PMID 22510321, 2012). "PHL and lymphoid lesions in general should be considered in the differential diagnosis of space occupying lesions of the liver in the absence of elevated levels of ordinary tumor markers including AFP and CEA." (PMID 21232116, 2011). "In addition, increased frequency of NDRG2 down-regulation was observed in patients with elevated AFP serum level (P = 0.006), late TNM stage (P = 0.009), poor differentiation grade (P = 0.002), tumor invasion (P = 0.004) and recurrence (P = 0.024)." (PMID 21676268, 2011). "An immunohistochemical study showed that CEA-positive and AFP-negative cells were present in the tumor." (PMID 22018031, 2011). "Thus, based on the tumor cells positive reactivity for GPC3, AFP, hepatocyte antigen, Hep Par 1, and CK18, we thought that the seminal vesicle mass should firstly be considered as a metastatic HCC lesion." (PMID 21443783, 2011). "When we analyzed the subgroups with all variables included at the time of diagnosis according to the BCLC tumor stage, the serum PIKVA-II (P < 0.001) and serum AFP (P = 0.023) in stage A, and serum PIVKA-II (P = 0.047) in stage C were risk factors for extrahepatic metastases in univariate analysis." (PMID 21985636, 2011). "In 2 cases and despite vascular involvement and tumor marker (AFP) failed to normalize, they were enrolled in surveillance program, as part of clinical trial and they were unable to have chemotherapy." (PMID 29147233, 2011).